ENSG00000259001 (ribonuclease P RNA component H1)
Gene: Long non-coding RNA gene on chromosome 14 (20,342,976 to 20,343,685, reverse strand). Ensembl gene ENSG00000259001.
Gene Ontology:
Molecular function: ribonuclease P activity
Biological process: tRNA processing
Cellular component: ribonuclease P complex
Diseases named in the same sentence as ENSG00000259001 in open-access papers:
ENSG00000259001 is named in the same sentence as 6 diseases in open-access papers, as found by Europe PMC text mining. Sharing a sentence is not in itself a finding about the gene and the disease. The quoted sentences say what the papers report.
neurodegenerative disease (1 paper, 2019). A disorder of the central nervous system characterized by gradual and progressive loss of neural tissue and neurologic function. "Multiple studies have revealed that the long non-coding RNA RPPH1 (Ribonuclease P RNA Component H1) is involved in disease progression of solid tumors and neurodegenerative diseases." (PMID 31645843, 2019).
ENSG00000259001 also shares sentences with these, for which no sentence is quoted: breast carcinoma (2 papers); cancer (1); colorectal cancer (1); leukemia (1); lung carcinoma (1).